STAT3 (signal transducer and activator of transcription 3)
Diseases named in the same sentence as STAT3 in open-access papers (continued):
Sharing a sentence is not in itself a finding about the gene and the disease.
breast cancer (continued). "After activated by IL-6 derived from metastasizing breast cancer cells, MDSCs can express both IL-6 and soluble IL-6Rα, which stimulate STAT3 phosphorylation through IL-6 trans-signaling in breast cancer cells." (PMID 27542274, 2016). "Constitutive activation of STAT3 is frequently observed in a variety of human cancers, including breast cancer, and plays a role in tumor progression and resistance to anti-cancer treatments by regulating the growth and survival of tumor cells." (PMID 26755645, 2016). "We found that AF1q activates STAT3 in human breast cancer cells by activating Src kinase through activation of the PDGF-B/PDGFR cascade." (PMID 27259262, 2016). "Recently, we reported that ZER abolishes CD44 expression through the inhibition of EGF/STAT-3 pathway in breast cancer cells." (PMID 26637807, 2016). "The active IL-6/STAT3/NF-κB positive feedback loop in CAFs from breast cancer patients shows an important role of this epigenetic switch in sustaining the activated phenotype of CAFs in the absence of cancer cells." (PMID 27248826, 2016). "JAK2/STAT3 promotes self-renewal of breast cancer stem cells, CD24−CD44+ is a marker for breast cancer stem cells." (PMID 26883017, 2016). "miR-7 represents a metastasis-suppressing miRNA that can reverse EMT by downregulating the signal transducer and activator of transcription 3 (STAT3) pathway in breast cancer cells." (PMID 27608009, 2016). "It has been shown that STAT3-survivin signaling mediated a poor response to radiotherapy in HER2-positive breast cancers." (PMID 27815936, 2016). "We have shown here that breast cancer cells and IL-6 persistently activate breast stromal fibroblasts through the stimulation of the positive IL-6/STAT3/NF-κB feedback loop." (PMID 27248826, 2016). "STAT3 phosphorylation in breast epithelial cells can be stimulated by paracrine signaling through IL-6 from both breast cancer cells and fibroblasts." (PMID 26840088, 2016). "In both BT474 and in SUM149 mammary carcinoma cells, constitutively active forms of STAT3, AKT and MEK1 were each shown to be a key protective molecular signal to suppress [ruxolitinib + MMF] -induced killing." (PMID 26981780, 2016). "Next, we analyzed 90 breast invasive ductal carcinoma (IDC) and 89 breast cancer brain metastasis specimens using immunohistochemistry for nuclear staining of pStat3, the activated form of Stat3." (PMID 25881542, 2015). "For instance, phosphorylated STAT3 promoted the stem-like cell phenotype in HER2-overexpressing breast cancer cells, which was resistant to Herceptin." (PMID 25686831, 2015). "A few studies have suggested that the activation of an IL6 inflammatory loop through STAT3 mediates trastuzumab resistance in HER2-positive breast cancer by expanding the cancer stem cell population and by promoting epithelial-mesenchymal transition." (PMID 26234940, 2015). "To determine the relationship between Stat3 and doxorubicin resistance in human breast cancer cells, we analyzed the expression of p-STAT3 and Stat3 in MCF7/ADR cells and MCF7 cells." (PMID 26169986, 2015). "In the current study, we sought to determine the role of Stat3 in the interaction between endothelial cells and tumor cells in breast cancer brain metastasis." (PMID 25881542, 2015). "Previous study revealed that STAT3/c-Myc pathway mediated progestin-induced suppression of miR-16 expression in mammary tumour cells." (PMID 25583328, 2015). "Altogether, our results indicated a direct interaction between Anxa2 and STAT3 in breast cancer cells." (PMID 26307676, 2015). "The STAT3 pathway can be positively regulated by mTOR signaling in human breast cancer stem-like cells." (PMID 26273424, 2015). "This concept is important for the exploitation of STAT3 dependency, as this highlights that different breast cancer subtypes require distinct targeting strategies." (PMID 25699542, 2015).
breast cancer (continued). "Activated or tyrosine phosphorylated STAT3 (pSTAT3) is found in approximately 50 % of breast cancers, with the highest expression levels identified in the leading edge of tumors, in areas of lymphovascular invasion and in axillary lymph nodes." (PMID 26234940, 2015). "Elucidating the role of STAT3 in breast cancer and identifying methods to inhibit STAT3 can be of benefit for developing cancer treatments." (PMID 26464811, 2015). "STAT3 signaling downstream of CXCR7 is involved in miR-101 regulation of breast cancer cell behaviors." (PMID 26360780, 2015). "Activation of the PI3K/AKT pathway, IL-6/JAK2/STAT3 pathway, and stem cell-like characteristics contribute to the poor outcomes of metastatic breast cancers." (PMID 26515594, 2015). "It was reported that the expression of STAT3 decreases in breast cancer cells transfected with lentivirus-based shRNAs targeting the mTOR gene." (PMID 25658305, 2015). "Together, we reveal an unexpected role for the tyrosine kinase SYK in maintaining STAT3 phosphorylation in basal-like breast cancer and provide a rationale for clinically testing SYK small-molecule inhibitors in this subclass of tumors." (PMID 25699542, 2015). "Accordingly, an IL-6/STAT3 pathway was preferentially active in CD44+/CD24- breast cancer stem cells and PTEN was shown to negatively regulate TIC manteinance through STAT3-dependent signalling." (PMID 26486080, 2015). "Mitochondrial S-P STAT3 enhances growth and invasion of the murine 4T1 breast cancer cells, both in vitro and in vivo, by increasing complex I coupling and reducing ROS production and apoptosis." (PMID 26106584, 2015). "Here we show that PYK2 exerts its effects on breast cancer migration and invasion predominantly through the STAT3 and MAPK signaling pathways." (PMID 26084289, 2015). "Inhibition of STAT3 leads to a reversion of the malignant phenotype of these cells, which indicates that it is a key mediator of breast cancer pathogenesis." (PMID 26464811, 2015). "This study revealed GRN as a novel STAT3 interactor that is necessary for constitutive as well as maximal cytokine-induced STAT3 transcriptional activity in breast cancer cells." (PMID 26000098, 2015). "Because GRN in breast cancer cells by immunoprecipitating STAT3 was detected in two independent experimental replicates and immunoblotting with a GRN antibody." (PMID 26000098, 2015). "EB also had similar inhibitory effects on the constitutively Tyr705-phosphorylated STAT3 in breast cancer MDA-MB-231 and MDA-MB-468 cells." (PMID 26010889, 2015). "Cucurbitacin D decreases cell proliferation and induces apoptosis by inhibiting Stat3 and NF-κB signaling in doxorubicin-resistant breast cancer cells." (PMID 26169986, 2015). "Elevated STAT3 phosphorylation levels have been reported in basal-like breast cancer cells and are required for breast tumor growth in vivo." (PMID 25699542, 2015). "It inhibits STAT3 dimerization, DNA binding, and STAT3-dependent transcription in breast cancer cells." (PMID 25710482, 2015). "Accordingly, MDA-MB-435 metastatic breast cancer cells, expressing high levels of Y-P STAT3 and of its target Bcl-2, are highly resistant to chemotherapy-induced apoptosis." (PMID 26106584, 2015). "In breast cancer cells, an autocrine signaling between STAT3 and RANTES is essential for tamoxifen resistance." (PMID 25638155, 2015). "Our previous studies have put forth Stat3 activation as an integral event in leptin signaling mediating oncogenic actions of leptin in breast cancer." (PMID 26036628, 2015). "STAT3 upregulation of miR21 has been documented in breast cancer, nasopharyngeal carcinoma, and hepatocellular cancer, and now shown in the present study relating to lung derived BMs." (PMID 26314961, 2015). "In this study, we found that cucurbitacin D decreased cell proliferation and induced apoptosis by inhibiting Stat3 and NF-κB signaling in doxorubicin-resistant breast cancer cells, MCF7/ADR." (PMID 26169986, 2015).
breast cancer (continued). "More interestingly, results from IHC analysis of human breast cancer tissues supported the contribution of Anxa2 to the activation of STAT3." (PMID 26307676, 2015). "Stat3 has been found to be persistently activated in e.g., breast, prostate ovary and pancreatic tumors and Stat5 in e.g., prostate and breast cancer, but also in various myeloproliferative diseases." (PMID 25809097, 2015). "While STAT3 activation can occur in any subtype of breast cancer, STAT3 activation is restricted largely to triple negative breast cancer cell lines, and STAT3 signaling has been shown to be important for the survival of triple negative breast tumors." (PMID 26697522, 2015). "Other researchers found that nuclear EGFR cooperates with STAT3 to regulate iNOS expression, and its nuclear expression is positively correlated to iNOS expression, a prognostic marker for breast cancer." (PMID 26497368, 2015). "In breast cancer cells, both genetic and epigenetic alterations have been shown to activate Stat3, including alterations in Her2/Neu, EGFR, BRCA1, and estrogen receptor." (PMID 25881542, 2015). "Apigenin induced caspase-dependent extrinsic apoptosis through inhibition of STAT3 signaling in HER2 overexpressing BT-474 breast cancer cells." (PMID 26500281, 2015). "In contrast, in breast cancer cells, the STAT3 is redox-sensitive and H2O2 decreases STAT3 binding to the consensus serum-inducible elements with inhibition of cell proliferation and reduced survival." (PMID 26273424, 2015). "It has been reported that STAT3 phosphorylation promotes angiogenesis various cancer types including breast cancer and the expression of angiogenic factor VEGF-A plays a vital role in STAT3-induced angiogenesis." (PMID 26474285, 2015). "Intriguingly, we observed that the Jak1/STAT3 pathway was significantly activated in trastuzumab-treated EGFRvIII+HER2+ breast cancer cells." (PMID 26474285, 2015). "A study of breast cancer has revealed that the EMT promotes cancer progression via a fibronectin-dependent STAT3 signaling pathway." (PMID 26530532, 2015). "In order to determine the cell signaling pathways mediating the thioridazine-induced tumor inhibition in the 4T1 breast cancer cells, the levels of Akt, STAT3 and NFκB p65 were analyzed." (PMID 26095429, 2015). "In the present study, we sought to determine the role of Stat3 in the interaction between tumor cells and endothelial cells in breast cancer brain metastases." (PMID 25881542, 2015). "Collectively, these results illustrated that STAT3 activation is significantly correlated with the mammosphere forming potential of breast cancer cells and its inhibition by a standard inhibitor or Shk potently reduce the mammosphere formation." (PMID 25973915, 2015). "STAT3 is constitutively activated in many types of human cancers, including breast cancer, and plays crucial roles in regulating tumor cell proliferation, survival, invasion, and angiogenesis." (PMID 26474285, 2015). "Accordingly, treatment of breast cancer cells with Stattic (a small-molecule inhibitor of Stat3) inhibited phosphorylation of Stat3 and increased expression of miR-34a, which was further increased with co-treatment with HNK." (PMID 26036628, 2015). "Quantitative phosphoproteomics revealed that SYK inhibition abrogates signaling to STAT3, explaining the selectivity for basal-like breast cancer cells." (PMID 25699542, 2015). "As the earlier results showed that Shk inhibits cell migration and invasion in breast cancer cells, we further examined the effect of STAT3, FAK and Src inhibitors on cell migration and invasion in MDA-MB 231 cells." (PMID 25973915, 2015).
breast cancer (continued). "In human breast cancer tissues, phospho-STAT3 expression was upregulated in the Anxa2 high expression group." (PMID 26307676, 2015). "For instance, the disruption of the STAT3 signaling has reduced tumor proliferation and angiogenesis, and has sensitized resistant breast cancer cells to doxorubicin." (PMID 25955018, 2015). "Many primary tumors contain constitutively activated STAT3, and 30%–60% of primary breast cancer specimens contain Tyr705-phosphorylated STAT3." (PMID 25784959, 2015). "Together, these evidences suggest that Anxa2 is required for EGF-induced activation of STAT3 in breast cancer cells." (PMID 26307676, 2015). "GRN enhanced STAT3 DNA binding and also increased the time-integrated amount of LIF-induced STAT3 activation in breast cancer cells." (PMID 26000098, 2015). "Given previous reports identifying GRN upregulation in breast tumor-instigating cells, we next examined the effects of extracellular GRN on STAT3 function in breast cancer cells." (PMID 26000098, 2015). "We from two breast cancer cell lines with constitutively confirmed this STAT3-GRN interaction by reciprocal coactive STAT3, it was selected for further analysis." (PMID 26000098, 2015). "Involvement of CSCs in tamoxifen resistance of breast cancer cells has been reported, which appears to be mechanistically linked with higher expression of CXCR4, STAT3, Sox2, EZH2, and lower expression of CD24." (PMID 26206152, 2015). "Of note, the pSTAT3-GS was positively correlated with IL6 (r = 0.4, P = 4.72e−05), which is the principal cytokine pathway through which STAT3 is activated in breast cancer and a surrogate of stromal reactivation." (PMID 26234940, 2015). "Functionally, TFF3 has recently been demonstrated to stimulate cellular invasion and metastasis of ER+ mammary carcinoma cells in a Src-STAT3 dependent manner." (PMID 26559818, 2015). "STAT3 is constitutively activated and/or overexpressed in many tumor cells including non-small cell carcinoma, breast carcinoma, melanoma, and leukemia cells, and the inhibition of STAT3 in these cells affects their survival and growth." (PMID 26010889, 2015). "Constitutive STAT3 tyrosine or serine phosphorylation has been detected in breast carcinomas, HNSCC, as well as lymphomas and leukemias, as well as prostate, melanoma, pancreas, ovarian and brain tumors." (PMID 26464811, 2015). "In this study, we show that in comparison with ‘young’ MSCs, senescent human umbilical cord mesenchymal stem cells (s-UCMSCs) significantly promote the proliferation and migration of breast cancer cells through the IL-6/STAT-3-dependent pathway." (PMID 25419563, 2014). "Same group has recently developed another STAT3 inhibitor termed BP-1-102 that represses the tumor growth of breast cancer cells in xenografts." (PMID 25202681, 2014). "Taken together, these findings indicate that while activated STAT3 can promote malignant cell behavior in breast cancer, important aspects of the biology of tumors characterized by activated STAT3 can be modulated by the presence of activated STAT5." (PMID 24762632, 2014). "In MCF7 human breast cancer cells, stable expression of an active STAT3 increased MMP-9 mRNA levels as well as transcriptional activation of the MMP-9 gene." (PMID 24743777, 2014). "STAT3 expression was assessed in the B cells from the peripheral blood of nine healthy individuals and 10 patients with breast cancer." (PMID 25013518, 2014). "In this study, the expression of STAT3 in the B cells of breast cancer patients was first detected and a mouse 4T1 breast cancer model was further applied for revealing a novel mechanism of tumor suppression by JSI124." (PMID 25013518, 2014). "The roles of STAT1 and STAT3 in breast cancer remain controversial since multiple studies have reported variable results between STAT isoform expression and clinical outcome, suggesting a degree of complexity in STAT signaling which is poorly understood." (PMID 24728078, 2014).
breast cancer (continued). "Accumulating evidence indicates that STAT3 plays a key role in maintenance of stem cell-like breast cancer cells, which have been shown to be related to tumor recurrence, metastasis and chemo-resistance." (PMID 24743778, 2014). "Benzyl isothiocyanate, an extract from cruciferous vegetables, blocks STAT3 activation induced by IL-6 in MDA-MB-453 breast cancer cells and PANC-1 pancreatic cancer cells." (PMID 24743778, 2014). "We discovered that WF induced the enrichment of breast cancer cells with stem-like phenotypes, via activation of STAT3." (PMID 25026286, 2014). "MiR-20b was also reported to involve regulation of VEGF expression by targeting HIF-1α and STAT3 in MCF-7 breast cancer cells." (PMID 25364498, 2014). "This study aimed to investigate further the roles of STAT1 and STAT3 in endocrine sensitive and resistant breast cancer using both cell line models and clinical samples from breast cancer patients." (PMID 24728078, 2014). "Constitutive activation of STAT3 signaling is observed in a number of neoplasms, including acute leukemia, breast cancer, squamous cell carcinoma of the head and neck, multiple myeloma and OvCa." (PMID 24887420, 2014). "STAT3 expression was upregulated approximately two-fold in the B cells from the patients with breast cancer compared with those in the healthy individuals (P=0.0015)." (PMID 25013518, 2014). "We demonstrated herein that HER2 overexpression plays an essential role in inducing STAT3 phosphorylation, which further leads to increased expression of stem cell markers in human breast cancer cells." (PMID 24297508, 2014). "Our data suggest that STAT3 activation is responsible for the stem cell marker expression in HER2-overexpressing breast cancer cells." (PMID 24297508, 2014). "Constitutive activation of STAT3 has been detected at high frequency in diverse human cancer cell lines and tissues, including breast cancer and gastric cancer." (PMID 25327561, 2014). "We also show that carnosol inactivated the Signal Transducer and Activator of Transcription 3 (STAT3) signaling pathway and efficiently inhibited tumor growth and metastasis in vivo of breast cancer cells." (PMID 25299698, 2014). "IL-6 is another typical proinflammatory cytokine with tumor growth effect, mainly by activating JAK tyrosine kinases and the transcription factor STAT3, as seen in lung, kidney, and breast cancer in which a high expression of STAT3 has been identified." (PMID 24901008, 2014). "Constitutive activation of STAT3 is involved in the formation of a variety of different tumors, including breast cancer." (PMID 25026286, 2014). "One peptide derived from helix-2 of STAT3 can specifically bind to the N-terminal domain of STAT3 and induce cell death in multiple breast cancer cell lines." (PMID 24743778, 2014). "Here, we demonstrate that our new herbal extract, SH003, suppresses both tumor growth and metastasis of MDA-MB-231 breast cancer cells via inhibiting STAT3-IL-6 signaling path." (PMID 24976685, 2014). "Further investigation indicated that the IL-6/JAK2/STAT3 pathway was preferentially active in CD44+CD24− breast cancer stem cells, and inhibition of JAK2 decreased the number of cancer stem cell number and blocked the growth of xenografts in mice." (PMID 24995504, 2014). "For example, blocking STAT3 in macrophages has been shown to activate anti-tumor immune responses in a murine model of breast cancer." (PMID 24995504, 2014). "Expression levels of STAT1 and STAT3 transcript were analysed in 550 breast cancers from publicly available gene expression datasets (GSE2990, GSE12093, GSE6532)." (PMID 24728078, 2014). "STAT3 is over-expressed and constitutively activated in many types of malignancies, such as breast cancer, HNSCC and glioma." (PMID 25514838, 2014). "Another group has demonstrated that the JAK2/STAT3 signaling was specifically required for the growth of CD44+/CD24− stem cell-like breast cancer cells in human tumors." (PMID 24297508, 2014).